PIN4 (peptidylprolyl cis/trans isomerase, NIMA-interacting 4)
Description:
Isoform 1 is involved as a ribosomal RNA processing factor in ribosome biogenesis. Binds to tightly bent AT-rich stretches of double-stranded DNA. Isoform 2 binds to double-stranded DNA.
Synonyms: Par14; hPar14; Par17; hPar17; hEPVH; EPVH
Tractability: Small molecule: a structure with a bound ligand is known. PROTAC: UniProt records ubiquitination sites on it; ubiquitination databases record sites on it; its protein half-life has been measured; a small molecule that binds it is known.
Target class: Enzyme
Gene: Protein-coding gene on chromosome X (72,181,353 to 72,302,926, forward strand). Ensembl gene ENSG00000102309.
Subcellular location: Nucleus, nucleolus (Isoform 1); Cytoplasm, cytoskeleton, spindle; Cytoplasm; Mitochondrion (Isoform 2); Mitochondrion matrix
Subcellular location (Human Protein Atlas): Nucleoli; Nucleoplasm; Mitotic chromosome
Gene Ontology:
Molecular function: protein binding; RNA binding; DNA binding; peptidyl-prolyl cis-trans isomerase activity
Biological process: rRNA processing
Cellular component: nucleolus; nucleoplasm; nucleus; cytoplasm; mitochondrial matrix; mitochondrion; spindle
Homologues: Orthologues: chimpanzee PIN4 (100% identical), macaque PIN4 (99% identical), mouse Pin4 (97% identical), guinea pig PIN4 (93% identical), dog PIN4 (92% identical), tropical clawed frog pin4 (87% identical), pig PIN4 (85% identical), zebrafish pin4 (82% identical), rat Pin4 (78% identical), Caenorhabditis elegans pinn-4 (73% identical), Drosophila melanogaster CG11858 (67% identical). Paralogues in human: PIN1 (36% identical).
Diseases named in the same sentence as PIN4 in open-access papers:
PIN4 is named in the same sentence as 12 diseases in open-access papers, as found by Europe PMC text mining. Sharing a sentence is not in itself a finding about the gene and the disease. The quoted sentences say what the papers report.
prostate carcinoma (3 papers, 2017 to 2024). A carcinoma that arises from epithelial cells of the prostate gland. "Tissue samples from 86 patients with prostate cancer were assessed by routine haematoxylin and eosin staining and immunohistochemistry (IHC) with a biomarker panel (Appl1/Sortilin/Syndecan-1) and a PIN4 cocktail (34βE12+P63/P504S)." (PMID 37704825, 2024).
prostate adenocarcinoma (2 papers, 2023 to 2025). "Immunohistochemistry was negative for CK20, CK5/6, PAX-8, TTF-1, PSA, and PIN4, but positive for PSAP and NKX3.1, consistent with mucin-producing prostate adenocarcinoma." (PMID 41293260, 2025).
COVID-19 (1 paper, 2022). A disease caused by infection with severe acute respiratory syndrome coronavirus 2. "Among them, six (ADK, DHFR, METAP2, PIN4, SC5D, and TMEM263) had matching risk factor genes showing consistent patterns, i.e., transcriptional downregulations increased the COVID-19 mortality risk." (PMID 35547187, 2022).
glioblastoma (1 paper, 2018). The most malignant astrocytic tumor (WHO grade IV). "Recent studies by Frattini and colleagues have shown that tyrosine-122 (Tyr-122) of Par14 (referred to as PIN4 in their studies) is phosphorylated in a subset of glioblastoma cases expressing the oncogenic fusion protein FGFR3-TACC3 (F3-T3)." (PMID 30314361, 2018). "Thus, the phosphorylation of PIN4 at Tyr-122 is an important intermediate step in F3-T3-induced activation of oxidative phosphorylation and mitochondrial biogenesis in glioblastoma cells." (PMID 30314361, 2018).
hepatocellular carcinoma (1 paper, 2023). A malignant tumor that arises from hepatocytes. "In this article, we found that endogenous PIN1 and PIN4 were upregulated in selected hepatocellular carcinoma (HCC) cell lines." (PMID 36760500, 2023).
cancer (5 papers, 2007 to 2023). A tumor composed of atypical neoplastic, often pleomorphic cells that invade other tissues. "It has been reported that PIN4 may contribute to higher invasiveness of recipient cancer cells." (PMID 36760500, 2023).
infection (4 papers, 2009 to 2025). The state of being infected such as from the introduction of a foreign agent such as serum, vaccine, antigenic substance or organism. "Other marker genes that have been shown to be expressed in giant cells during late stage of infection include auxin resistant 1 (Aux1), auxin efflux carrier 4 (PIN4), endo-1,4-beta-glucanase (ENG), pectate lyase like (PLL), and Formin 2A." (PMID 41209832, 2025). "A detailed study of the role of PIN3 and PIN4 in the infection process is currently under way in our laboratories." (PMID 31976537, 2020). "In three independent infection experiments pin2, pin3, pin4, and pin7 mutants showed a 10 to 25% reduction in number of cysts." (PMID 19148279, 2009). "Notably, two other PIN genes, PIN3 and PIN4, also appear to be induced upon infection with S. indica." (PMID 31976537, 2020). "During the HBV course of infection, Juglone, PiB, ATRA, 6,7,4′-THIF, KPT6566, and EGCG-mediated inhibition of PIN1 and PIN4 significantly lowered HBV transcriptional activities without affecting total levels of covalently closed circular DNA (cccDNA)." (PMID 36760500, 2023).
tumor (3 papers, 2021 to 2023). "PIN4 staining was used to approximate the presence and percentage tumor area in PDE tissues and facilitate analysis of Ki67 staining in benign and malignant tissue regions." (PMID 35406480, 2022). "Compared to its kinase-dead form (K508M mutant), FGFR3–TACC3 increased PIN4 phosphorylation at Tyr122, thereby promoting mitochondrial respiration and ATP production and tumor progression." (PMID 34732230, 2021). "Recently, Frattini and colleagues identified PIN4, as a novel substrate of the FGFR3–TACC3 fusions, was required for reactive oxygen species (ROS)-mediated induction of peroxisome proliferator-activated receptor gamma coactivator 1-alpha (PGC1α) and tumor growth." (PMID 34732230, 2021). "Since the endogenous PIN1 and PIN4 levels remained higher in HBV replicating and non-replicating HCC-derived cell lines, we examined PIN1 and PIN4 levels in the biopsied tumor and non-tumor adjacent liver tissues obtained from eight patients of HBV-associated HCC." (PMID 36760500, 2023).
PIN4 also shares sentences with these, for which no sentence is quoted: Alzheimer disease (1 paper); Glucose intolerance (1); nematode infection (1); primary biliary cirrhosis (1).